DCLK1 (doublecortin like kinase 1)
Diseases named in the same sentence as DCLK1 in open-access papers (continued):
Sharing a sentence is not in itself a finding about the gene and the disease.
cancer (continued). "Recent advances in DCLK1 research underscore its isoform-specific functions in cancer." (PMID 40775208, 2025). "It has been reported that DCLK1 promotes cancer growth via the PI3K/mTOR/Akt pathway." (PMID 40863727, 2025). "A research investigation has devised an innovative targeted drug delivery system employing DCLK1-functionalized, folic acid-conjugated HST encapsulated within chitosan nanoparticles (CFH-DCLK1) to preferentially target cancer stem cells (CSCs) within the context of CRC." (PMID 41415832, 2025). "Besides, we have also used the GEPIA2 database to explore the correlation between DCLK1 and key target genes of several signaling pathways which have been tested for DCLK1 involvement in stem cell-like traits in other cancers." (PMID 39781521, 2025). "Importantly, published studies have also demonstrated that DCLK1 is essential for maintaining CSC-like phenotypes in several human cancers 7-9." (PMID 39781521, 2025). "Doublecortin-like kinase 1 (DCLK1) is a promising therapeutic target for cancer." (PMID 40775208, 2025). "Doublecortin-like kinase 1 (DCLK1) promotes a variety of malignant cancers in their progression." (PMID 38980538, 2024). "DCLK1 is an important marker of cancer stem cell and an important anti-tumour target." (PMID 38062554, 2024). "Thus, the interplay between DCLK1 and miRNAs underscores a complex regulatory network that is crucial for maintaining cellular homeostasis and modulating cancer-related pathways." (PMID 38928187, 2024). "Overexpression of DCLK1 is reported in colon, gastric, renal, pancreatic, and other cancers." (PMID 39683266, 2024). "The majority of our understanding regarding DCLK1 function is confined to its role in cancer." (PMID 39845838, 2024). "Growing evidence indicates DCLK1 overexpression within the CCA cancer stem cells (CSCs) subpopulation and in serum samples from patients with CCA, and might be a potential predictive biomarker for early diagnose in CCA." (PMID 38980538, 2024). "Moreover, DCLK1 has been identified as a cancer stem cell (CSC) biomarker in various cancers, which has received considerable attention recently." (PMID 38062554, 2024). "Additionally, silencing DCLK1 has been shown to hinder the progression of pancreatic ductal adenocarcinoma and colon cancer, indicating its tumour-promoting role in cancer." (PMID 37887321, 2023). "Our previous study also pointed out that DCLK1 inhibition could restore drug sensitivity of TKI-resistant cancer cells by attenuating tumor cells stemness in lung adenocarcinoma." (PMID 37069669, 2023). "Recent work has focused on the role of different isoforms of DCLK1 in cancer progression." (PMID 38003596, 2023). "Yet, a consistent preference for a single DCLK1 isoform across all cancers remains elusive." (PMID 38003596, 2023). "Although some DCLK1 missense mutations were shown to impact protein function and stability, no specific cancer driver mutation in DCLK1 has been identified or functionally validated." (PMID 36979969, 2023). "The number of DCLK1+ tuft cells increases with age, as cancer progresses in Pten-null prostates." (PMID 37386128, 2023). "Increased levels of DCLK1 have also been reported in various human cancers." (PMID 36896602, 2023). "However, increased DCLK1 expression is observed in colon cancers, suggesting that transcription from the beta-promoter and upregulation of the DCLK1-S isoforms are vital for cancer progression." (PMID 38003596, 2023). "Several reviews have provided in-depth discussions of the consequence of DCLK1 overexpression to cancer progression, including the functional implications of different DCLK1 protein isoforms generated from the same gene, as well as the effects of therapeutic or genetic inhibition." (PMID 36979969, 2023). "DCLK1’s effect on cancer is also influenced by its interactions with other proteins." (PMID 37762326, 2023). "Consequently, DCLK1 has become a target for cancer treatment and a biomarker for early cancer prevention." (PMID 37762326, 2023).
cancer (continued). "DCLK1 serves a major regulatory involvement in cancer aggressiveness." (PMID 37443105, 2023). "However, patients with low WNT5A levels and high DCLK1 levels in their cancer tissue (Group 4) had a significantly worse prognosis than those grouped based only on high DCLK1 expression." (PMID 37998393, 2023). "DCLK1 has multiple isoforms, and recent research suggests that they might have contrasting roles in cancer and other diseases." (PMID 38003596, 2023). "Two previous meta-analyses across multiple studies and cancer types showed that DCLK1 overexpression correlates with advanced clinical stage, lymph node metastasis, poorly differentiated cancers, poor overall survival, and reduced anti-tumor immune responses within the tumor microenvironment." (PMID 36979969, 2023). "DCLK1 has been found to play a critical role in the development of cancer." (PMID 37762326, 2023). "Furthermore, DCLK1-overexpressing cancer cells are observed for lower X ZO-1, which is an epithelial marker and increased mesenchymal markers, including ZEB1 and vimentin." (PMID 36250024, 2022). "In addition, previous studies have shown that DCLK1 plays a vital role in various cancer metastases." (PMID 36250024, 2022). "Additionally, three studies offered that LRRK2, an inhibitor of DCLK1, can prevent DCLK1 kinase activity and has the effect of anti-cancer activity." (PMID 35717205, 2022). "Moreover, this review summarizes the effect of upregulated DCLK1 in several cancers along with the signaling pathways." (PMID 36250024, 2022). "In addition, there is strong experimental evidence that involves DCLK1 in the acquisition of many hallmarks of cancer, including proliferation, invasion, metastasis, angiogenesis, and cell resistance." (PMID 35717205, 2022). "Moreover, DCLK1 is a cancer stem cells marker in intestinal tumor cells and contributes to breast cancer cell metastases." (PMID 36369000, 2022). "Although DCLK1’s specific mechanism is unclear, cancer therapy targeting it has improved." (PMID 36250024, 2022). "Therefore, our findings suggested that DCLK1 promoted 5‐fluorouracil resistance in CRC by CCAR1/β‐catenin pathway‐mediated cancer stemness." (PMID 35522902, 2022). "DCLK1 is functionally involved in maintaining cancer stemness and the process of EMT." (PMID 35444536, 2022). "Due to the considerable substantiation of elevated DCLK1 in a variety of malignancies, the inhibition of the putative DCLK1 gene might be considered one of the defining characteristics of cancer." (PMID 36250024, 2022). "Therefore, our findings reveal that DCLK1 promotes 5‐fluorouracil resistance in CRC by CCAR1/β‐catenin pathway‐mediated cancer stemness." (PMID 35522902, 2022). "Furthermore, investigating the DCLK1 mechanism and its role in chemo-resistant cancer cells help in finding DCLK1-specific targets and small molecules for inhibiting DCLK1." (PMID 36250024, 2022). "However, the exact molecular mechanism by which DCLK1 drives the aggressive phenotype of cancer cells is incompletely determined." (PMID 35910805, 2022). "Factors expressed by cancer cells that upregulates DCLK1 expression." (PMID 36250024, 2022). "Many studies report that the biliary tract originates from the primitive gut and has a very similar morphology, particularly in the extrahepatic tract, and many researchers have demonstrated that DCLK1 (Doublecortin-like kinase 1) is a cancer stem cell marker in the intestinal tum." (PMID 36077857, 2022). "Having proved that DCLK1 promoted 5‐fluorouracil resistance through CCAR1/β‐catenin pathway‐mediated cancer stemness, we wondered whether targeting DCLK1 could suppress 5‐fluorouracil resistant CRC cells." (PMID 35522902, 2022). "Notably, accumulating evidence has shown that the specific genes (POU2F3, DCLK1) expressed in tuft cells are involved in vital processes related with carcinogenesis and cancer development." (PMID 36569325, 2022).
cancer (continued). "There is an emerging appreciation that distinct DCLK1 isoform signatures may exist in cancer development and progression, calling for in-depth studies to rationally design isoform-specific modulators." (PMID 34545159, 2021). "Herein, we demonstrate that small-molecule kinase inhibitor DCLK1-IN-1 strongly inhibits DCLK1 phosphorylation and downregulates pluripotency factors and cancer stem cell (CSC) or epithelial-mesenchymal transition (EMT)-associated markers including c-MET, c-MYC, and N-Cadherin in RCC cell lines." (PMID 34830884, 2021). "DCLK1 has also been proposed as a novel cancer stem cell marker in a plethora of human cancers." (PMID 33350586, 2021). "The development of DCLK1-IN-1, the first specific inhibitor of DCLK1 kinase, by the Gray lab provides a valuable material for studying the effects of DCLK1 kinase inhibition in the context of cancer." (PMID 34830884, 2021). "Therefore, regulation of DCLK1 is complicated, but the inhibition of its kinase activity seems to be a promising strategy in cancer treatment and the elimination of CSCs." (PMID 34445192, 2021). "Notably, the proteins which had the biggest fold change in differentiated hVM1 clone 32 cells, GAP43, DCLK1, and EEF1A2, are implicated in several cancers." (PMID 35126116, 2021). "Future studies on the biological functions of DCLK1 microtubule-binding and kinase activity during the initiation and progression of cancer cell proliferation and migration will provide fundamental insights into how DCLK1 contributes to this malady and how it can be adequately targeted." (PMID 34310279, 2021). "DCLK1 is widely recognised as a therapeutic target of interest in cancer." (PMID 34545159, 2021). "We explicitly addressed this point here to avoid over-interpretation of the results presented and to encourage other groups investigating DCLK1-IN-1 in RCC or other cancer types to build on this work in finding a meaningful concentration range for this important new DCLK1 targeting modality." (PMID 34830884, 2021). "Our results uncover a novel intramolecular regulation of microtubule binding within a prominent family of MAPs and may have implications for DCLK1’s known roles in tumor development and cancer progression." (PMID 34310279, 2021). "In a study with HT-29 and SW-480, montelukast prevented LTD4-induced colony formation and disrupted colonospheres as well as downregulation of cancer stem cell markers (ALDH1 and DCLK1), suggesting the beneficial effect in minimizing cancer stem cells of CysLT1R inhibition." (PMID 35008546, 2021). "Thus, additional functional studies are needed to further elucidate the oncogenic impact of DCLK1 in promoting the malignant potential of cancer cells and its role in the adverse prognosis noted in HNSCC." (PMID 34336664, 2021). "Furthermore, the compound suppressed expression of cancer stem cell marker proteins DCLK1, ALDH1, and CD133." (PMID 33924995, 2021). "However, expression of DCLK1 was also associated with impaired DNA repair, upregulation of WNT/β-catenin, RAS, PI3K/AKT and VEGF signaling, suggesting a multifaceted role of DCLK1 in cancer initiation and progression." (PMID 34336664, 2021). "Furthermore, there was a reduction in expression of cancer stem cell marker proteins DCLK1, CD44, CD133, Oct-4, and ABCG2." (PMID 32094348, 2020). "Triple therapy resulted in a significant decrease in DCLK1 expression compared to the mice treated with gemcitabine alone, suggesting that cancer stemness may be inhibited by the combination treatment." (PMID 32203220, 2020). "miR-613 could inhibit cancer cell proliferation, migration, invasion and promotes apoptosis by targeting numerous oncogenes, including DCLK1, Fzd7, and SphK2.miR-613 had been stated to be down-regulated in different cancers and act as a tumor suppressor." (PMID 32592365, 2020). "Interestingly, besides other effects, saffron is also able to target cancer stem cells (CSC) via the decrease of DCLK1." (PMID 32756469, 2020).
cancer (continued). "In addition, circle-derived genomic rearrangements further contribute to the aberrant expression of cancer-relevant genes, such as doublecortin-like kinase 1 (DCLK1) and telomerase reverse transcriptase (TERT)." (PMID 32928268, 2020). "However, further studies of DCLK1-expressing TCs and their biological effect in normal conditions and in initiating cancer will be needed to safely target DCLK1." (PMID 33348546, 2020). "Finally, monoclonal antibodies and chimeric antigen receptor T-Cells (CAR-T) based on DCLK1 have demonstrated potential as novel cancer immunotherapies." (PMID 33348546, 2020). "Overall, DCLK1 is reaching maturity as an anti-cancer target and therapies directed against it may have potential against CSCs directly, in remodeling the tumor microenvironment, and as immunotherapies." (PMID 33348546, 2020). "DCLK1 is a marker of gastrointestinal tuft cells which drive the type II immune response to inflammatory injury and have been reported to play an important role in cancer initiation and development in various cancers." (PMID 31979136, 2020). "Prior studies have shown that a subset of Dclk1-positive CSCs survive due to autophagy in response to curcumin and that increased Dclk1 correlates with the malignant status and poor outcome in malignant tumors." (PMID 31040926, 2019). "Additionally, we have immunostained several human tissues (normal and cancer) with CBT-15 (DCLK1 mAb)." (PMID 31878090, 2019). "Considering that the EMT and MAPK pathways are obvious candidates involved in cancer progression and metastasis in many cancer types, we checked whether DCLK1 affects these signaling pathways." (PMID 31223610, 2019). "Since cancer stem cells (CSCs), which comprise a small proportion of total cancer cells, have special capacities for self-renewal, differentiation and tumor formation and Dclk1 is a validated marker of CSCs, we next stained tumors from either organ with antibody for Dclk1." (PMID 31040926, 2019). "Mechanistically, we found that activation of the EMT program and ERK MAPK pathway may jointly contribute to DCLK1-mediated cancer metastasis." (PMID 31223610, 2019). "Interestingly, all these markers are involved in regulation of both EMT and CSCs and are controlled by DCLK1 expression in cancer models." (PMID 31684193, 2019). "DCLK1 expression in the normal pancreas is isolated to glandular exocrine cells, while it is overexpressed in both tumor epithelial and stromal cells in the cancer tissue." (PMID 31467540, 2019). "Furthermore, this also provides a strong rationale to utilize the cell surface expression of DCLK1 to deliver anti-cancer payloads or for developing DCLK1-based CAR-T therapy." (PMID 31878090, 2019). "Significant association existed between DCLK1 level and OS, indicating that DCLK1 may act as a potential marker for predicting survival outcomes in patients with cancer." (PMID 29246000, 2017). "In this family, DCLK1 has been shown to be a cancer stem cell marker in intestinal tumours." (PMID 28195176, 2017). "All studies were retrospective, and most of studies adopted immunohistochemistry (IHC) to detect the expression of DCLK1 in cancer tissues samples that composed of malignant cell and a supporting stroma, while one adopted reverse transcription-polymerase chain reaction (RT-PCR)." (PMID 29246000, 2017). "In our meta-analysis, the value of DOR was 13, indicating that DCLK1 could be used as a biomarker for the diagnosis of malignant tumors." (PMID 29246000, 2017). "The mean diagnostic odds ratio (DOR) was 12.70 (95% CI = 6.68–24.15), indicating that DCLK1 level in cancer tissues could be helpful in the diagnosis of malignant tumors." (PMID 29246000, 2017). "Eleven studies investigated the expressions of DCLK1 in different clinical stages of cancers." (PMID 29246000, 2017).
cancer (continued). "Although DCLK1 has recently been identified as having a key role in regulating pluripotency factors in cancer cells, our current findings demonstrate that Dclk1 is essential for maintaining the expression of epithelial pluripotency factors and self-renewal during crypt regeneration after injury." (PMID 27876863, 2016). "Interestingly, the critical signaling pathways NOTCH, NFKB, and WNT that are involved in regulating both EMT and CSCs are controlled by DCLK1 expression in cancer models." (PMID 27335684, 2016). "Moreover we also found increased expression levels of the Dclk1 protein, an intestine cancer stem cell marker, within tumor sections from both LTD4- and PGE2- treated mice." (PMID 27388564, 2016). "Together, these studies strongly suggest that DCLK1+ cells may be the cells of origin for cancer, and are suspected to be responsible for cancer recurrence and the development of deadly metastases that are resistant to standard therapies." (PMID 27335684, 2016). "DCLK1 has been proposed as a cancer stem cell marker for gastrointestinal cancers." (PMID 26621833, 2016). "DCLK1 was more frequently found in luminal cancers than basal-like and HER2-OE subtypes, associated with IBC-NED and potentially an independent favorable prognostic factor in these cancers." (PMID 26621833, 2016). "Therefore, further studies are required to assess the reliability of Dclk1 as a cancer stem cell marker." (PMID 27811361, 2016). "From a therapeutic point of view, targeting DCLK1 using emerging small molecules may open novel avenues for the treatment of cancer, including NETs, in various organs." (PMID 26622789, 2015). "Finally, we note that different therapeutic interventions targeting DCLK1 in cancer are currently under development." (PMID 25605241, 2015). "However, we believe that this data in addition to the functional similarities between renal tubules and the small intestinal epithelium merits further investigation of DCLK1 in kidney diseases in addition to cancer." (PMID 25605241, 2015). "It is well known that DCLK1 colocalizes with both microtubules and the actin cytoskeleton, but these associations and their significance in cancer have not been investigated in depth." (PMID 25605241, 2015). "Given the increasingly recognized role of EMT derived stem cells in cancer progression and metastasis, we hypothesize that DCLK1 may contribute to the metastatic process." (PMID 25723399, 2015). "The functional significance of DCLK1 in cancer has only been explored recently." (PMID 24885928, 2014). "Targeting Dclk1 with siDCLK1-NPs reduces the dysregulation in miRNAs, EMT, and pluripotency associated with cancer risk, suggesting that targeting Dclk1 in patients even with advanced cancer may be a therapeutic option for intestinal and/or other solid tumors." (PMID 25211188, 2014). "Moreover, the restricted expression of DCLK1 in a limited set of normal cells and its upregulation and tumor-stem cell status in cancer tissue make it an ideal target for cancer therapy." (PMID 24885928, 2014). "DCLK1 has been targeted on the genetic level in some cancers with promising results." (PMID 24885928, 2014). "Dclk1 is overexpressed in many cancers, including colon, pancreas, liver and esophagus." (PMID 25211188, 2014). "Here we propose the hypothesis that DCLK1-mediated overexpression of these pluripotency factors in cancer cells may drive them towards a poorly differentiated phenotype, which may in turn facilitate the process of EMT." (PMID 24040120, 2013). "This difference may be partly attributed to high expression of DCLK1 in cancer cells compared to human normal liver tissues or cultured hepatocytes." (PMID 24260365, 2013). "Finally, we contend that beyond its status as a putative marker of quiescent stem cells and/or Tuft cells, DCLK1 plays a central role in the initiation, progression and dissemination of cancer cells." (PMID 24040120, 2013). "Additionally, DCLK1 functions as a cancer stem cell marker in the colon." (PMID 40839695, 2025).